LINC03042 (long independently transcribed non-coding RNA 3042)
Synonyms: C8orf86; FLJ43582
Gene: Long non-coding RNA gene on chromosome 8 (38,510,834 to 38,529,044, reverse strand). Ensembl gene ENSG00000196166.
Diseases named in the same sentence as LINC03042 in open-access papers:
LINC03042 is named in the same sentence as 1 disease in open-access papers, as found by Europe PMC text mining. Sharing a sentence is not in itself a finding about the gene and the disease.
LINC03042 shares sentences with these, for which no sentence is quoted: osteosarcoma (1 paper).